COL3A1 (collagen type III alpha 1 chain)
Diseases named in the same sentence as COL3A1 in open-access papers (continued):
Sharing a sentence is not in itself a finding about the gene and the disease.
Hepatic steatosis (4 papers, 2018 to 2025). Steatosis is a term used to denote lipid accumulation within hepatocytes. "In control diet fed mice, Nrf2 deficiency was nonconsequential, while Nrf1 and combined deficiency exacerbated the effect, as demonstrated by hepatic steatosis as well as significant or trending increases in hepatic triglyceride and expression of Ccl2, Ccnb1, Col1a1, Col3a1, Ihh, and Tnfrsf12a." (PMID 39125617, 2024). "The findings from this study suggest that miR29c may provide geese tolerance against severe hepatic steatosis by modulating energy homeostasis and tissue growth and that its function is mediated by its target genes, Col3a1, Sgk1, and Insig1." (PMID 30400792, 2018). "Based on the functions of Col3a1, Sgk1 and Insig1 in cell growth, we conclude that miR29c may participate in tissue growth during the development of goose fatty liver, which enables the goose liver to tolerate severe steatosis at the end of the overfeeding period." (PMID 30400792, 2018). "The results suggested that Col3a1, Sgk1 and Insig1 were most likely to be the target genes of miR29c in the development of goose fatty liver, which was supported by the complete match of the 3’ UTR sequences of the genes to the core sequence of goose mature miR29c (note: Col3a1 had two matches)." (PMID 30400792, 2018).
steatosis (4 papers, 2018 to 2025). Increased lipid within the cytoplasm of cells. "HCC section staining revealed signaling upregulation in ki67, severe fibrosis, and steatosis in WD and CCl4 mice and detected Col3a1 gene expressions." (PMID 35163556, 2022).
type 2 diabetes (4 papers, 2016 to 2022). "Key mediators of the injury responses in islets transgenic for human IAPP or those from individuals with type 2 diabetes include STAT3, NF-κB, ESR1 and CTNNB1 by transcription factor analysis and COL3A1, NID1 and ZNF800 by gene regulatory network analysis." (PMID 34554282, 2022).
Arthritis (3 papers, 2013 to 2022). Inflammation of a joint. "Mutations in the COL3A1 gene have been linked to arthritis and bone disorders." (PMID 36167601, 2022). "This indicated that COL3A1 expression increased over time and correlated with arthritis severity in CIA rats." (PMID 35831853, 2022).
breast tumor (3 papers, 2008 to 2016). "COL3A1, COL5A1 and COL11A1 are fibrillar collagens, which act as “tracks” for metastatic invasion of breast tumors into secondary organs." (PMID 23383328, 2013). "Our module showed the breast tumor specific co-expression between PDGFRL and collagens COL3A1, COL5A2 and COL6A3." (PMID 18366601, 2008).
cardiomyopathy (3 papers, 2024 to 2025). A disease of the heart muscle or myocardium proper. "Accordingly, RT-qPCR analysis confirmed that miR199a-5p reduced the expression of the cardiomyopathy marker genes nppa and Mhy7 as well as the genes expression of the collagen marker Col1a1, Col1a2, and Col3a1." (PMID 38956062, 2024). "Molecular evidence of cardiomyopathy, including inflammation marker (Tnd and Il6), fibrosis marker (Col1a1 and Col3a1), and hypertrophy marker (Nppa, Nppb, and Myh7), significantly increases when Rab7 was knocked out." (PMID 38837607, 2024). "Col15a1‐deficient mice exhibit non‐proto‐fibrillar protein deposits in the cardiac myocardium interstitium, along with an abnormal increase in the Col1a1/Col3a1 ratio, heightened myocardial stiffness, reduced elasticity, and decreased myocardial compliance, ultimately leading to cardiomyopathy." (PMID 39592912, 2025).
cervical cancer (3 papers, 2020 to 2024). A primary or metastatic malignant neoplasm involving the cervix. "The expression levels of Col1A1, Col3A1, Col4A1 and HIF-1α were positively correlated with P4HA2 levels in TCGA cervical cancer cohort (P < 0.001)." (PMID 32226497, 2020).
diabetic cardiomyopathy (3 papers, 2021 to 2025). Diabetic cardiomyopathy is a disorder of the heart muscle in people with diabetes. "Moreover, cardiac fibrosis was also alleviated by QLQX treatment in mice with STZ-induced diabetic cardiomyopathy as evidenced by Masson staining and the expression levels of Col1a1 and Col3a1." (PMID 34336956, 2021). "The salient findings from the present study support that Cyp1a1, a significantly upregulated DEG, has the highest connectivity in the PPI interaction network among the top five hub genes (Cyp1a1, Cyp2e1, Col1a1, Col3a1, Col1a2) to affect the cardiac function in STZ-induced diabetic cardiomyopathy." (PMID 35387435, 2022).
glomerulosclerosis (3 papers, 2021 to 2022). A hardening of the kidney glomerulus caused by scarring of the blood vessels. "Consistent with marked glomerulosclerosis in UNx-Renin mice, ECM-associated gene expression changes were more pronounced in UNx-Renin mice, in which additional markers of fibrogenesis were significantly upregulated, including Col1a1, Col3a1, Col6a1, Col6a2 and Mmp7." (PMID 34494644, 2021).
lung adenocarcinoma (3 papers, 2020 to 2022). A carcinoma that arises from the lung and is characterized by the presence of malignant glandular epithelial cells. "The expression of COL1A1, COL1A2, and COL3A1, members of the collagen family, is increased in lung adenocarcinomas and is associated with its poor prognosis." (PMID 34326696, 2021). "COL3A1 and COL1A2 higher expressed in tumor samples were hub genes in a miRNA–gene interaction network and related to the survival time of lung adenocarcinoma." (PMID 36138770, 2022). "Hsa-mir-145 formed the third regulatory module for lung adenocarcinoma c with lncRNA C1orf220, which ranked second in potential lncRNAs, and mRNAs (COL1A2, COL3A1, SPP1, TIMP1 and CDH1)." (PMID 36138770, 2022). "Six genes (COL3A1, COL1A2, OGN, COL15A1, ASPN, and MXRA5) and three miRNAs (hsa-miR-29c-3p, hsa-let-7c-5p, and hsa-miR-29b-3p) were related to the survival time of lung adenocarcinoma (LUAD)." (PMID 32300359, 2020).
lymph node metastasis (3 papers, 2018 to 2023). "We also found a significant association between patients with lymph node metastasis and overexpression of BMP7 (47.4%, P=0.005), CALD1 (42.1%, P=0.020), CDH1 (52.6%, P=0.001), COL3A1 (42.1%, P=0.020), EGFR (47.4%, P=0.005), ERBB3 (57.9%, P=0.000), PLEK2 (47.4%, P=0.024), and TCF4 (52.6%, P=0.001)." (PMID 34527572, 2021). "In our study, there was a notable correlation between COL3A1 and lymph node metastasis." (PMID 29967488, 2018). "In addition, the expression levels of COL3A1, COMP, and ZAP70 were positively related to the risk of lymph node metastasis." (PMID 29967488, 2018). "COL3A1 expression levels were not significantly different from clinical parameters such as sex, age, smoking status, alcohol history, clinical status, and lymph node metastasis." (PMID 36039012, 2023).
oral cancer (3 papers, 2011 to 2023). "This study provides novelty by showing that mRNA levels of MAOB, NAB2, COL3A1, NPIPB4, CYP27A1, and SIAE were significantly reduced in the saliva of oral cancer patients." (PMID 31963366, 2020).
ovarian tumor (3 papers, 2016 to 2022). "Increased expression of COL3A1 has been reported in CIS-resistant ovarian tumors." (PMID 35328460, 2022). "A recent report identified COL3A1 in a 7-gene signature related to stage in SC patients contributing to extracellular matrix interactions and mitosis, supporting our findings that COL3A1 may be a promising prognostic factor for ovarian tumor progression." (PMID 31533654, 2019).
pelvic organ prolapse (3 papers, 2007 to 2021). Abnormal descent of a pelvic organ resulting in the protrusion of the organ beyond its normal anatomical confines. "The collagen 3 alpha 1 (COL3A1) rs1800255 polymorphism has been reported to be associated with women pelvic organ prolapse (POP) susceptibility, but the results of these previous studies have been contradictory." (PMID 33930075, 2021). "We investigated whether single nucleotide polymorphisms (SNPs) of collagen type 1 alpha 1 (COL1A1), collagen type 3 alpha 1 (COL3A1), and lysyl oxidase-like (LOXL) 1 and 4 were associated with the onset of pelvic organ prolapse (POP) in Japanese women." (PMID 33413618, 2021). "In contrast, we recently reported a syndrome of joint hyperlaxity, easy bruising, pelvic organs prolapses, premature rupture of the membranes and rectal bleeding associated with a non-glycine sequence variant of the COL3A1 gene (P435T)." (PMID 17640391, 2007).
pneumothorax (3 papers, 2020 to 2024). Abnormal presence of air in the pleural cavity. "Therefore, we believe that the occurrence of pneumothorax, changes in lung CT, and various clinical symptoms are caused by the COL3A1 gene mutation." (PMID 37800821, 2023). "In this report, we present a rare case, both COL3A1 and TSC2 gene mutations were appeared in this patien that manifested as recurrent pneumothorax, hemoptysis and intrapulmonary cavitary lesions." (PMID 37800821, 2023).
preeclampsia (3 papers, 2019 to 2025). Preeclampsia is a hypertensive disorder of pregnancy that is characterized by new-onset hypertension with proteinuria presenting after 20 weeks of gestation, and depending on mild or severe forms may initially present with severe headache, visual disturbances, and hyperreflexia. "Additionally, urinary peptidome profiling, using a 22-marker panel including collagen type III alpha one chain (COL3A1), was investigated for clinical diagnostics of preeclampsia." (PMID 35884419, 2022).
scrapie (3 papers, 2011 to 2014). A fatal disease of the nervous system in sheep and goats, characterized by pruritus, debility, and locomotor incoordination. "In our results, three types of collagen (COL1A2, COL3A1 and COL12A1) exhibited downregulation in sheep with natural scrapie and might be related to the loss of their neuroprotective role." (PMID 21629698, 2011). "The gene and protein expression profiles and protein distribution of six potential genetic biomarkers (i.e., CAPN6, COL1A2, COL3A1, GALA1, MT2A and MTNR1B) are presented here for both the early and terminal stages of scrapie in five different brain regions." (PMID 23497022, 2013). "We and others have previously reported altered expression of COL1A2, COL3A1 and COL12A1 and other ECM related genes in the CNS of sheep infected with scrapie and other prion diseases and in leukocyte-depleted splenic cells from scrapie-infected mice." (PMID 24450868, 2014).
thyroid cancer (3 papers, 2012 to 2025). "Apparently, the average relative expression levels of COL3A1 in breast, liver, thyroid cancer samples were higher than their normal counterparts." (PMID 23282184, 2012).
adenoma (2 papers, 2016 to 2018). A neoplasm arising from the epithelium. "COL3A1 transcription level was increased from adenoma to carcinoma, indicating an involvement of COL3A1 in carcinogenesis." (PMID 26741506, 2016).
arachnodactyly (2 papers, 2019 to 2024). "Genetic variants in genes including TGFBR1, TGFBR2, TGFB2, TGFB3, SMAD2, and SMAD3 result in Loeys–Dietz syndrome and are reported to cause Marfan-like phenotypes and variants in FBN2 and COL3A1 result in congenital contractural arachnodactyly and Ehlers–Danlos syndrome type IV." (PMID 38791509, 2024). "In particular, aortic ectasia resulted significantly influenced by FBN1 rare pathogenic variants and by FBN1, COL1A1 and COL3A1 VUS, arachnodactyly resulted influenced by FBN1 rare pathogenic and VUS rare variant; MYH11 pathogenic variants and FBN1 VUS resulted associated with ectopia lentis." (PMID 31536524, 2019).
Atopic Dermatitis (2 papers, 2023 to 2024). "Furthermore, single nucleotide polymorphisms within the COL3A1 and COL6A5 genes have been associated with atopic dermatitis, revealing distinct genotype-phenotype relationships." (PMID 38404668, 2024).
atrial fibrillation (2 papers, 2013 to 2017). A disorder characterized by an electrocardiographic finding of a supraventricular arrhythmia characterized by the replacement of consistent P waves by rapid oscillations or fibrillatory waves that vary in size, shape and timing and are accompanied by an irregular ventricular response. "Another study has observed that COL3A1 is targeted by miR-29 as a participant in the mechanism of atrial fibrillation." (PMID 24079748, 2013).
bladder urothelial carcinoma (2 papers, 2017 to 2022). "Moreover, we found a significant difference of expression of COL3A1 between infiltrating bladder urothelial carcinoma and superficial bladder cancer, indicating that COL3A1 maybe correlated with the invasive bladder cancer and non-invasive bladder cancer." (PMID 29050298, 2017).
breast invasive carcinoma (2 papers, 2022 to 2023). "TCGA analysis of TGF-β target genes (e.g., COL1A1, COL3A1, COL5A2, COL6A1, COL6A3, TIMP1, and CTGF) further identified overactivation of TGF-β signaling pathway in a broad spectrum of solid tumors, in particular in breast invasive carcinoma and pancreatic adenocarcinoma tissues." (PMID 37328484, 2023).
carcinoid (2 papers, 2021). "The expression of COL1A2, COL3A1, COL5A2, ITGA5, and ITGB1 in SCLC, LCNEC, and typical carcinoid samples in the GSE1037 profile, as compared with normal samples, were determined using a GEO2R online analyzer (log FC>2 and adjusted P<0.05) and then compared to the data from our cohort." (PMID 34458147, 2021).
Chronic colitis (2 papers, 2021 to 2023). A chronic inflammatory disease of the large intestine (colon, cecum and rectum). "DSS-induced chronic colitis attenuated biliary septal fibrosis, which may be attributed to less BA accumulation mediated inhibition of activated HSCs (Col1a1, Col1a2, Col3a1 and Timp1) without affecting PFs in Mdr2−/− mice." (PMID 37280200, 2023).
chronic kidney disease (2 papers, 2012 to 2019). Impairment of the renal function secondary to chronic kidney damage persisting for three or more months. "It has been reported that HIF-1α exerted an effect in hypoxia- and chronic kidney disease-induced fibrosis, while genetic knock-down of HIF-1α in renal epithelial cells led to a significant reduction in collagen deposition, including COL1A1 and COL3A1." (PMID 30536131, 2019). "The top 25 upregulated genes showed evidence of matrix protein replacement with increased collagen synthesis (Col1a1 and Col3a1) and cellular infiltration (Cxcl1, Lyzs, Ccl5, Lyz2, Lyz, C3 VCAM1 and Ear2), consistent with the histological presence of chronic kidney disease in the mice." (PMID 22970174, 2012).
Cirrhosis (2 papers, 2024 to 2025). A chronic disorder of the liver in which liver tissue becomes scarred and is partially replaced by regenerative nodules and fibrotic tissue resulting in loss of liver function. "Analyzing the cirrhosis dataset (GSE25097) revealed that the expression of SLC27A5 was negatively correlated with that of fibrosis‐related genes such as ACTA2, COL1A1, and COL3A1." (PMID 37957540, 2024).
dermatofibrosarcoma protuberans (2 papers, 2017 to 2023). Dermatofibrosarcoma protuberans (DFSP) is a rare infiltrating soft tissue sarcoma, generally of low grade malignancy, arising from the dermis of the skin and characteristically associated with a specific chromosomal translocation t(17;22). "The equivalent pathognomonic COL1A1-PDGFB gene fusion found in human dermatofibrosarcoma protuberans was found in a dermatofibrosarcoma protuberans-like canine tumor, with the equivalent fusion found being COL3A1-PDGFB in the dog." (PMID 29218302, 2017).
endothelial dysfunction (2 papers, 2024 to 2025). In vascular diseases, endothelial dysfunction is a systemic pathological state of the endothelium (the inner lining of blood vessels) and can be broadly defined as an imbalance between vasodilating and vasoconstricting substances produced by (or acting on) the endothelium. "Elevated expression of COL3A1 has been linked to endothelial dysfunction and vascular remodeling, which may increase vessel fragility and promote plasma leakage in inflammatory conditions." (PMID 40124360, 2025). "Consequently, these findings indicate that COL1A1, COL3A1, and POSTN could potentially be used as biomarkers to assess the severity of endothelial dysfunction in the progression of ED." (PMID 38467692, 2024).
Hiatus hernia (2 papers, 2009 to 2017). The presence of a hernia in which the upper part of the stomach, i.e., mainly the gastric cardia protrudes through the diaphragmatic esophageal hiatus. "We also show genetic association between COL3A1 and hiatus hernia in the same adult case control cohort." (PMID 19398442, 2009). "In the present study, based on four independent GORD patient collections, we show that COL3A1 is associated with GORD and implicated as being a risk factor for hiatus hernia." (PMID 19398442, 2009). "Gastroesophageal reflux and hiatus hernia may both be linked to COL3A1 although no allele has yet been identified." (PMID 28704418, 2017). "A region on chromosome 2, containing collagen type III alpha 1 (COL3A1), was identified (LOD = 3.3) in families with dominant transmission of GORD, stratified for hiatus hernia (HH)." (PMID 19398442, 2009). "We identified linkage to the COL3A1 region in a set of families in which GORD and hiatus hernia is transmitted." (PMID 19398442, 2009).
hypertrophic cardiomyopathy (2 papers, 2020 to 2025). A condition in which the myocardium is hypertrophied without an obvious cause. "Genes involved in hypertrophic cardiomyopathy such as Myh6 and Acta2, cardiac fibrosis such as Mmp2 and Col3a1, were all highly up-regulated by AB surgery, and hispidulin treatment significantly down-regulated these genes." (PMID 33324687, 2020).
kidney damage (2 papers, 2022 to 2025). "Col3A1 kidney mRNA and protein in urine was also found to be elevated in a puromcyin aminonucleoside (PAN)- induced nephropathy rat model." (PMID 40169735, 2025).
multiple sclerosis (2 papers, 2013 to 2015). A progressive autoimmune disorder affecting the central nervous system resulting in demyelination. "In contrast, the overexpression of the collagenous type II transmembrane protein (COL25A1) leads to AD-like pathology and different collagens, including COL1A1 and COL3A1, are induced in multiple sclerosis lesions." (PMID 23497022, 2013). "COL1A1, COL3A1, COL5A1, and COL5A2 chains were induced significantly in active multiple sclerosis lesions and even more in inactive lesions." (PMID 26691002, 2015).
myocarditis (2 papers, 2018 to 2019). Myocarditis is a condition that is characterized by inflammation of the heart muscle (myocardium). "Next we determined expression of collagen genes in the heart during myocarditis and found that BPA exposure in drinking water significantly increased expression of collagen I (Col1a1) (p = 0.005) and collagen III (Col3a1) (p = 0.02) compared to control water." (PMID 31551929, 2019).